CD4 (CD4 molecule)
Diseases named in the same sentence as CD4 in open-access papers (continued):
Sharing a sentence is not in itself a finding about the gene and the disease.
endometriosis (continued). "CD25+CD4+FOXP3+ T cells were found in all the examined endometriosis tissue samples." (PMID 20923543, 2010). "The percentage of FOXP3+ cells within the subpopulation of CD4+ lymphocytes was statistically significantly higher in the tissue samples from the patients with endometriosis as compared with the percentage found in the tissue samples from the patients who had developed ectopic pregnancies." (PMID 20923543, 2010). "However, a significantly lower frequency of CD3+CD4+CD25HighCD39+CD73+ cells was observed in the endometriosis group compared to controls (M: 1.98; IQR: 0.0377–3.17 vs. M: 2.25; IQR: 0.50–4.08; p = 0.0483), suggesting a reduction in systemic immune tolerance among these patients." (PMID 38781760, 2024). "Experiments in a mouse model on the therapeutic potential of the anti-CTLA-4 antibody have shown that it may be an important tool to inhibit the progression of endometriosis by regulating the overproduction of CD4+ CD25+ Treg cells, a phenomenon repeatedly reported in the literature." (PMID 35805112, 2022). "Experiments on the therapeutic potential of the anti-CTLA-4 antibody in a mouse model have shown that it may be an important tool in inhibiting the progression of endometriosis by regulating the overproduction of CD4+CD25+ Treg cells, a phenomenon repeatedly described in the literature." (PMID 33668701, 2021). "The concentration of transforming growth factor-β (TGF-β), another key cytokine involved in CD4+Foxp3+ Treg function, was lowest in the peritoneal fluid from healthy controls, elevated in women with early stage endometriosis and highest in women with advanced stages of endometriosis." (PMID 25275597, 2014). "Besides cytotoxic T lymphocytes, characterized as CD8+ T cells, helper T cells or, namely, CD4+ T cells are further diminished in their activity in PF from patients with endometriosis, probably because PF homeostasis breakdown suppresses activation of helper T cells." (PMID 23843796, 2013). "Furthermore, the peritoneal fluid of women with endometriosis displays increased levels of immunosuppressive cytokines, such as IL-10 and IL-12, which may inhibit the activity of activated CD4 + T cells and contribute to immune evasion by endometriotic lesions." (PMID 40313549, 2025). "Phenotypic analysis of mononuclear cells revealed a significantly lower percentage of CD45+, CD3+, CD4+, CD8+, and CD19+ cells in the patient population with endometriosis compared to the healthy women in the control group." (PMID 40862752, 2025). "The analysis of lymphocyte subpopulations in ascitic fluid demonstrated a significantly lower CD4/CD8 ratio in HGS-OC patients than in other histotypes and endometriosis (p = 0.016)." (PMID 40723209, 2025). "We observed markedly higher expression of TLR2, TLR3, TLR4, TLR7, TLR8, and TLR9 on CD4+, CD8+, and CD19+ lymphocytes in the endometriosis group, indicating their active participation in modulating immune responses in the disease setting." (PMID 40862752, 2025). "In the case of differentiation between endometriosis phenotypes, AUC values ≥ 0.85 were obtained for CD8 + TLR3, CD4 + TLR4, and CD19 + TLR3 in the comparisons of PE vs. CC and DIE vs. CC, suggesting their importance in distinguishing these disease subtypes." (PMID 40862752, 2025). "Our current study showed significant differences in levels of CD4+ and CD8+ T cells, CD8+ Tem cells, eosinophils, monocytes, Th1 cells, memory B cells, aDCs, and pDCs in endometriosis tissue samples." (PMID 35303800, 2022). "To determine if induction of endometriosis altered peripheral immune cell populations, we identified nTregs (CD4+CD25+Foxp3+), iTregs (CD4+CD25−Foxp3+) and Th17 cell populations in blood samples collected over time." (PMID 35102185, 2022). "The high expression of CD160 is believed to be one of the factors that plays a role in decreasing CD4+ expression in women with endometriosis because the bond between CD160 and its ligand inhibits the activation of CD4+ T cells." (PMID 36313261, 2022).
endometriosis (continued). "However, the proportions of CD4+ memory resting T cells (P < 0.001), gamma delta T cells (P = 0.031), M1 Macrophages (P = 0.020), M2 Macrophages (P < 0.001), and neutrophils (P = 0.002) in endometriosis tissues were significantly higher than those in normal tissues." (PMID 35378934, 2022). "The authors performed immunofluorescence staining of iNKT cells for the markers CD3, CD4, and CD1d (counterstained with DAPI) in endometriosis lesions and healthy peritoneum from nine patients." (PMID 35576870, 2022). "The results of the present study show for the first time that PF from women with advanced endometriosis displays immunomodulatory activity toward both unstimulated and CD3/CD28/IL-2-stimulated CD4+ T cells." (PMID 34360900, 2021). "Like other researchers, this groupintroduced CD4+CD25+FoxP3+ as Tregs and reportedsimilar numbers of blood Tregs in endometriosis andcontrol samples." (PMID 33098386, 2020). "Although some studies demonstrated increased levelsof CD4+CD25+FoxP3+ cells in the PF andectopic tissue of endometriosis subjects, we did notdetect this increase in our study." (PMID 33098386, 2020). "Our study revealed the role of MAIT cells in endometriosis and different profiles of their three subpopulations (i.e. CD8 MAIT, CD4 MAIT and DN MAIT cells)." (PMID 31615517, 2019). "In accordance with other studies, our results showed that for endometriosis patients in both PB and PF the CD8 MAIT cells were the major subpopulation and CD4 MAIT cells were the minority, with DN MAIT cells in between." (PMID 31615517, 2019). "Our study revealed increased frequencies and numbers of PD-1-positive and PD-L1-positive CD3+CD4+ and CD3+CD8+ T cells, as well as CD19+ B cells in endometriosis patients." (PMID 30595667, 2018). "In our study of a rat model of endometriosis, we examined the influence of GXXYW on cell proliferation and apoptosis of endometriotic cells, and the percentages of CD3+ lymphocytes, CD4+ lymphocytes, and CD8+ lymphocytes in the spleens of rats." (PMID 25691906, 2015). "Additionally, a significant increase in CD4+/CD8+ T cell infiltrate occurrence and size was reported in endometriosis samples (eutopic and ectopic) compared with controls (p < 0.01)." (PMID 36613776, 2022). "The increase of the CD4+/CD8+ T cell ratio and decrease of anti-inflammatory IL-10 could be involved in the pathogenesis of endometriosis and may secondarily affect the functions of monocytes and macrophages." (PMID 35303800, 2022). "The number of CD4+ iNKT cells expressing CCR7 (35.6 ± 30.6 vs. 31.6 ± 31.0; p = 0.439) and the number of DN iNKT expressing CCR7 (11.18 ± 15.87 vs. 6.76±14.08; p = 0.801) were similar between the endometriosis and control groups." (PMID 35576870, 2022). "Furthermore, significantly higher percentages of CD4+/CTLA-4 and CD8+/CTLA-4 T lymphocytes were observed in patients with endometriosis and intraoperative adhesions." (PMID 35805112, 2022). "There was an increased number of CD4+ iNKT cells expressing IL-17 in the peripheral blood of patients with endometriosis and severe dysmenorrhea compared to those with mild/absent dysmenorrhea (11.1 ± 4.7 vs. 4.3 ± 4.0; p = 0.038)." (PMID 35576870, 2022). "Pathological immune response in the peritoneal environment is responsible for the implantation of ectopic endometrium and maintenance of immunological self-tolerance mediated by CD4+CD25+ Treg cells, which were found in the peritoneal fluid of women with endometriosis in higher concentrations." (PMID 36142815, 2022). "Furthermore, a higher CD4/CD8 ratio and an increased concentration of each subset was found in the peritoneal fluid of patients with endometriosis." (PMID 35628346, 2022). "Data suggest that significantly higher percentages of CD4+/CTLA4 and CD8+/CTLA4 T lymphocytes have been observed in patients with endometriosis and intraoperative adhesions, implicating that there is a possible correlation between the ratio of CD8+ T/CD4+ T and endometriosis-related infertility." (PMID 36142815, 2022).
endometriosis (continued). "According to the results of the CIBERSORT, MCP-counter, and ImmuCellAI methods, we found that the abundances of T cells, CD4+ T cells, follicular helper T (Tfh) cells, and CD8+ T cells in the eutopic endometria of women with endometriosis were higher than those in the endometria of normal controls." (PMID 34539624, 2021). "In patients with endometriosis and coexisting adhesive disease, negative correlation of T lymphocytes CD4+CTLA-4+ with the percentage of NK cells CD3-CD16+CD56+ was demonstrated (R = −0.622, p < 0.001)." (PMID 33668701, 2021). "The phenotypic characterization of different PBMC populations revealed significantly lower frequencies of CD3+ T, CD4+ T, and Treg cells in endometriosis compared to non-endometriotic controls." (PMID 32231038, 2020). "In a manner independent of cycle phase, the subpopulations of activated dendritic cells, CD4 T effector memory phenotype cells, eosinophils, macrophages M1, and natural killer T cells (NKT) were all higher in stage I-II endometriosis compared to those in healthy controls." (PMID 31941945, 2020). "We found no systemic deviation in frequency of CD4+ T subsets in different stages of endometriosis; however, Th17 cells were increased in the PF in patients with advanced endometriosis compared to controls." (PMID 33098386, 2020). "CD4 and CD8 MAIT cells could be drivers in the development of in endometriosis, whereas DN MAIT cells might be protectors for the host." (PMID 31615517, 2019). "Seven immune cells, namely, activated CD4 + T cells, gamma-delta T cells, CD56 dim natural killer cells, eosinophils, monocytes, natural killer T cells, and plasmacytoid dendritic cells, were significantly different between the Endometriosis and Control groups (p < 0.05)." (PMID 40313549, 2025). "Additionally, recent studies have shown a significant increase in the proportion of CD4 + CD25hiFoxp3+ cells within the PF, but not in peripheral blood, of endometriosis patients, as opposed to those without the disease." (PMID 39309679, 2024). "A host of studies confirmed that the numbers of CD4+CD25+ forkhead box protein 3(FOXP3)+ Treg cells significantly increased in the peritoneal lesions of women with ovarian endometrioma compared with women without endometriosis." (PMID 36865552, 2023). "Similarly, no significant changes were observed in the percentages of CD8 T cells among total mononuclear cells and no variations revealed in CD8 T cell rates and CD4/CD8 ratio among CD3+ cells in endometriosis regardless of the stage." (PMID 37497226, 2023). "In this way, these cells could promote the development of endometriosis.We did not locate any article that compared all four subsets of CD4+ T cells in both PB and PF between early and advanced stages of endometriosis and controls." (PMID 33098386, 2020). "However, a significant decrease in CD3+CD4+CD25HighCD39+CD73+ cells was noted in the endometriosis group (M: 1.98; IQR: 0.0377–3.17 vs. M: 1.25; IQR: 0–5.08; p = 0.0483), suggesting a potential alteration in systemic immune tolerance mechanisms in endometriosis." (PMID 38781760, 2024). "To see whether the PF from the patients with endometriosis and the control subjects may affect in vitro generation of Treg and Th17 cells we evaluated specific phenotype changes of the unstimulated and CD3/CD28/IL-2-stimulated CD4+ T cells following their 5-day culture." (PMID 34360900, 2021). "The percentages of CD4+CTLA-4+ and CD8+CTLA-4+ T lymphocytes were significantly higher in women with endometriosis and coexisting adhesion disease than in women with endometriosis but no adhesion disease." (PMID 33668701, 2021). "Percentages of T CD4+CTLA-4+ and B CD19+CTLA-4+ lymphocytes were not significantly different between patients with endometriosis and the control group." (PMID 33668701, 2021). "In CD4+ T and CD19+CTLA-4+ B cells, no such differences were observed between the group of patients with endometriosis and the control group." (PMID 33668701, 2021).
endometriosis (continued). "In patients with endometriosis and pelvic pain syndrome, a weak negative correlation was observed between the concentration of soluble CTLA-4 antigen in peripheral blood plasma and the percentage of CD4+CD25+highFoxp3 Treg cells (R = 0.31, p = 0.043)." (PMID 33668701, 2021). "Therefore, we analyzed the relative abundance of Treg (CD4+/FOXP3+) cells in the PF of women with and without endometriosis." (PMID 32572831, 2020).
systemic sclerosis (62 papers, 2010 to 2025). A chronic disorder, possibly autoimmune, marked by excessive production of collagen which results in hardening and thickening of body tissues. "According to recent research, increased JMJD3 expression on CD4+ T cells in individuals with systemic sclerosis was associated with a large drop in H3K27me3." (PMID 36874364, 2023). "Immunophenotyping of 20 systemic sclerosis cases using a 36-marker CyTOF panel revealed 18 significant alterations in peripheral blood mononuclear cells (PBMCs), highlighting the involvement of CD4+, CD8+, mucosal-associated invariant T cells, and B-cell subsets in pathogenic chronic inflammation." (PMID 38726007, 2024). "elucidated FLI1’s pivotal role in alloreactive CD4+ T cell activation and differentiation in Graft-versus-host disease, while its involvement in Treg induction in systemic sclerosis has been highlighted in other studies." (PMID 39140108, 2024). "in CD4+ T cells from patients with systemic sclerosis, treatment with all-trans retinoic acid, a natural derivative of vitamin A, increases the expression of FOXP3 and, subsequently the proportion of Treg cells by promoting demethylation of the FOXP3 promoter." (PMID 38510251, 2024). "A recent study pointed out that there was a high expression of JMJD3 on CD4 + T cells accompanied by a significant decrease in H3K27me3 in patients with systemic sclerosis." (PMID 36874364, 2023). "We also examined the expression of HLA-DR in apoptotic cells in pSS, since CD4+CTLs are HLA class II restricted and we had previously reported that apoptotic cells in systemic sclerosis and IgG4-RD expressed HLA-DR39,40." (PMID 36104369, 2022). "A trend towards increased frequency of CD4+PD1+ T cells has also been reported in systemic sclerosis." (PMID 35371068, 2022). "The CD8+ T cell apoptotic rate was higher than that of CD4+ T cells in the systemic sclerosis patients due to a low level of NF-κB transcription factor and increase of CD4+:CD8+ T cells." (PMID 34258301, 2021). "In this study, the integrated analysis of DNA methylation, gene expression, promoter capture Hi-C, and genetic data potentially unveils novel functional relationships in CD4+ T cells of patients with systemic sclerosis." (PMID 32977850, 2020). "It was reported that differences in CD4+CD25+Foxp3+ and CD4+CD25+CD127- iTreg frequencies exist in the blood of patients with systemic scleroderma." (PMID 22905732, 2012). "Studies of systemic sclerosis have revealed that overexpression of CD11a in CD4+ T cells may mediate the immune abnormalities and fibrotic processes of the disease and show a possible relationship between this molecule and B cells." (PMID 37039643, 2023). "Indeed, in systemic sclerosis (SSc), the importance of CD4+ T cells to the pathogenesis has been indicated." (PMID 35967355, 2022). "Interestingly, CD4+CD8+ T cells have recently been associated with multiple diseases, and cells can be suppressive or cytotoxic, depending on conditions (cancer, HIV, systemic sclerosis)." (PMID 35619708, 2022). "Finally, PlexinD1 neutralization regulates the systemic sclerosis patients serum-induced cytokine production by CD4+ T cells." (PMID 32971928, 2020). "These two pathways indicated that T cell was differentiated to Th1 subset after AHST, which was consistent with a recent study displaying predominant reconstitution of Th1 CD4+T after autologous CD34+ stem cell transplantation in patients with systemic sclerosis." (PMID 22384093, 2012). "This study investigated the role of IL-35 in systemic sclerosis (SSc) patients, focusing on CD4+ T cell response and immunomodulatory cytokine production." (PMID 37445745, 2023). "Likewise, in non-infectious diseases such as acute coronary syndrome and systemic sclerosis, cytotoxic CD4+ T cells were capable of causing damages to endothelial cells." (PMID 33752798, 2021). "ATRA treatment of systemic sclerosis (SSc) CD4+ T cells induces Foxp3 expression with enhanced immunosuppressive functionality." (PMID 34239942, 2021).
systemic sclerosis (continued). "Current reports on the changes in peripheral blood regulatory T cell (Tregs) to CD4+ T cell ratio in systemic sclerosis (SSc) patients are varied in their conclusions." (PMID 28317890, 2017). "Patients with systemic sclerosis have been found to have reduced Th1/increased Th2 populations, and a bias towards effector CD8 and naïve CD4 T cells, and reduced γδ T cells." (PMID 40766316, 2025). "In addition to its role in T-lymphocyte migration, SDF-1 is also a co-stimulator of CD4+ T cells and plays a role in HIV progression, microvascular complications among systemic sclerosis patients, and progression of carotid artery stenosis." (PMID 25029540, 2014). "In SLE and systemic sclerosis (SS), AHST induced immunologic self-tolerance by both depletion of autoreactive T cells and restoration of immune regulatory network mediated by CD4+CD25+T cell; the T cell subpopulation recovered from immune-suppression until approximately one year." (PMID 22384093, 2012). "DNA methylation profiling of CD4+ T cells from Grave’s Disease (GD), RA, SLE, and Systemic Sclerosis (SSc) patients share a predominant hypomethylation pattern." (PMID 34769338, 2021).